GOLGA8F (golgin A8 family member F)
Synonyms: DKFZp434P162
Tractability: No criterion of Open Targets' tractability assessment is met for any kind of drug.
Gene: Protein-coding gene on chromosome 15 (28,378,621 to 28,392,021, forward strand). Ensembl gene ENSG00000153684.
Gene Ontology:
Cellular component: cis-Golgi network; Golgi apparatus
Homologues: Orthologues: mouse Golga2 (47% identical), dog GOLGA2 (45% identical), tropical clawed frog golga2 (34% identical), zebrafish golga2 (31% identical), Drosophila melanogaster GM130 (23% identical), Caenorhabditis elegans golg-2 (20% identical), rat Golga2l1 (5% identical). Paralogues in human: GOLGA8G (100% identical), GOLGA8S (91% identical), GOLGA8M (81% identical), GOLGA8J (81% identical), GOLGA8H (81% identical), GOLGA8K (80% identical), GOLGA8T (80% identical), GOLGA8N (79% identical), GOLGA8O (79% identical), GOLGA8Q (79% identical), GOLGA8R (78% identical), GOLGA8A (72% identical), and 6 more.